PINK1 (PTEN induced kinase 1)
Diseases named in the same sentence as PINK1 in open-access papers (continued):
Sharing a sentence is not in itself a finding about the gene and the disease.
Parkinson disease (continued). "It is regulated by several proteins including Parkin and PTEN-induced kinase 1 (PINK1), whose mutations have been observed in patients with neurodegenerative diseases such as Parkinson’s disease and AD." (PMID 37465125, 2023). "This is parsimonious with a gut-linked early pathophysiology of Parkinson’s disease as well as with mutations in the PINK1 and PRKN ubiquitin ligase genes as risk factors for an early-onset form of Parkinson’s disease." (PMID 37174637, 2023). "PINK1 mutations cause early-onset autosomal recessive Parkinson's disease, whereas its expression protects against various toxic insults in models of Parkinson's disease." (PMID 35875478, 2022). "Because mitophagy, sensed by PINK1 and effected by Parkin, is critical for mitochondrial quality control, Parkinson’s disease caused by mutations of these genes is widely considered a mitochondrial disorder." (PMID 35326504, 2022). "Loss-of-function mutations in the PINK1 gene, which regulates mitophagy, are linked to familial Parkinson’s disease." (PMID 35628458, 2022). "And then, in 2010, four outstanding studies revealed the molecule mechanism of PINK1/Parkin-mediated mitophagy and its pathogenic mechanisms in the pathogenesis of Parkinson’s disease." (PMID 35923469, 2022). "In support of the role of PINK1/Parkin in mitochondria, mutations in the PINK1 and Parkin genes are found to cause early onset of Parkinson’s disease that is also associated with mitochondrial dysfunction." (PMID 35874823, 2022). "At the same time, the main factors leading to disruption of mitophagy in Parkinson’s disease are mutations in the Pink1 and Parkin enzymes." (PMID 36432705, 2022). "It will be possible to use mitophagy activators in the treatment of Parkinson’s disease in patients with mutations in the Pink1 and Parkin proteins." (PMID 36432705, 2022). "Core components of the mitophagy process are PINK1 and Parkin, which mutations are linked to Parkinson’s Disease." (PMID 36092697, 2022). "The autosomal recessive pattern of inheritance of PINK1 mutations suggests that PINK1 is neuroprotective and therefore loss of PINK1 function causes early-onset parkinsonism." (PMID 35585060, 2022). "In C. elegans, the loss of heat shock proteins hsp-70 intensifies the protein oxidation and the dAergic neuronal degeneration through inhibition of the transcriptional upregulation of PINK1, a gene that has, in fact, been linked to Parkinson’s disease." (PMID 36291605, 2022). "The mutation of the PARK6 locus on the short arm of chromosome 1 was discovered in a large Italian family with autosomal recessive early-onset parkinsonism in 2001, and the PINK1 gene is suggested to be one of the causal genes that can result in parkinsonism." (PMID 36157077, 2022). "Autosomal recessive mutations in the genes encoding the mitochondria‐targeted kinase PINK1 and the E3 ubiquitin (Ub) ligase Parkin are associated with parkinsonism." (PMID 36250243, 2022). "Mutations of the human PINK1 gene are also found to cause early onset Parkinson’s disease, a neurodegenerative disorder with the pathological feature of mitochondrial dysfunction." (PMID 35874823, 2022). "Dysfunctional mitophagy, and specifically, mutations in PINK1 and/or Parkin, can lead to the development of neurodegenerative diseases with Parkinson’s disease as the main example." (PMID 35391620, 2022). "For example, mutations in PINK1 and Parkin are associated with early-onset forms of Parkinson’s Disease (PD) while mutations in MFN2 are associated with axonal forms of Charcot-Marie-Tooth disease 2 (CMT2) and hereditary motor and sensory neuropathies (HMSN)." (PMID 36339819, 2022). "Early-onset Parkinson's disease is often linked to defects in specific genes, including PINK1 and Parkin, that encode proteins involved in mitophagy, the process of selective autophagic elimination of damaged mitochondria." (PMID 35311891, 2022).
Parkinson disease (continued). "PINK1 is a causative gene for Parkinson’s disease and the corresponding protein has been identified as a master regulator of mitophagy—the autophagic degradation of damaged mitochondria." (PMID 35203326, 2022). "Autosomal recessive forms of early-onset Parkinson’s disease are known to be associated with mutations in PINK1 and the E3 ubiquitin ligase Parkin, which have been found to promote mitophagy, a specialized form of autophagy degrading damaged mitochondria." (PMID 35625553, 2022). "Juvenile Parkinson’s disease is caused, in rare instances, by mutations in PINK1 or PARK2 (Parkin) mitophagy genes." (PMID 35326504, 2022). "A study on Parkinson’s disease showed that mutation in the PINK1/PARKIN triggered mitochondrial dysfunctions, and led to nigral neurodegeneration to promote the early commencement of the disease." (PMID 36307395, 2022). "Mutations in mitophagy regulators, such as PTEN-induced putative kinase 1 (PINK1) and the cytosolic E3 ligase Parkin, are known as causal genes for familiar Parkinson disease." (PMID 36158192, 2022). "This evidence raises the potential of GLP-1R agonists for treating both rare and more common neurological diseases with a strong mitochondrial component e.g. PRKN- or PINK1-associated Parkinson’s Disease." (PMID 35970890, 2022). "Mutations in genes involved in mitochondrial metabolism are linked to Parkinson’s disease, including genes such as PINK1, PRKN, SNCA, and PARK7." (PMID 35628458, 2022). "As observed in Parkinson's disease, the loss of PINK1/Parkin‐mediated MDVs formation is due to the inability of mitochondria to remove the oxidized/ damaged proteins, leading to mitochondrial dysfunction." (PMID 35582908, 2022). "Mutations in PINK1 that prevent it from phosphorylating its substrates is one of the most significant causes of a recessive form of Parkinson’s disease (PD)." (PMID 33498615, 2021). "Shortly after PINK1 was identified as a Parkinson’s disease-associated gene in 2004, research focusing on the biological roles of PINK1 have mainly cantered on neuronal diseases." (PMID 33546409, 2021). "Overall, the paper established a functional association between Pink1-Parkin and mitochondrial selective autophagy, which is involved in the pathogenesis of Parkinson’s disease." (PMID 34912814, 2021). "PTEN-induced putative kinase 1 (PINK1) mutations related to the recessive genetic forms of parkinsonism, in the cerebellum of PD patients in Purkinje neuron and in several neuron types of dentate nuclei have been detected." (PMID 34421548, 2021). "Disruptions in mitochondrial homeostasis or the expression of PINK1 and Parkin leads to mitochondrial impairments and associated disorders such as Parkinson’s disease." (PMID 33686350, 2021). "The most studied is the so-called PINK1/Parkin pathway, which is associated with ubiquitylation of several mitochondrial proteins that were initially found to be related to Parkinson’s disease." (PMID 35201480, 2021). "Current research has identified PINK1 and Parkin mutations as the most common causes of Parkinson’s disease." (PMID 34912814, 2021). "Apart from α-Synuclein accumulation, Parkinson’s pathology can also be attributed to mutations in genes such as PINK1 (PTEN-induced putative kinase 1), DJ-1, PRKN (parkin) and LRRK2 (leucine-rich repeat kinase 2)." (PMID 34830158, 2021). "Mutations in genes encoding either PINK1 or Parkin are implicated in the pathogenesis connected with Parkinson’s disease along with mutations to LRRK2 (leucine-rich repeat kinase 2), which is also found in the OMM." (PMID 33498615, 2021). "During the process, two genes are essential, encoding the PINK1 and the cytosolic E3 ubiquitin ligase Parkin, which are found to be mutated in Parkinson’s disease (PD)." (PMID 34422828, 2021).
Parkinson disease (continued). "PTEN-induced kinase 1 (PINK1) and Parkin, two mitochondrial proteins linked to mitophagy and Parkinson's disease, have been shown to actively inhibit mitochondrial-derived vesicles and mitochondrial antigen presentation in favor of mitophagy." (PMID 33953963, 2021). "For example, cryptic splice site usage resulting in exon 7 skipping of PINK1 causes early-onset Parkinson’s disease, while increased inclusion of exon 10 in MAPT causes frontotemporal dementia with parkinsonism." (PMID 33414398, 2021). "For example, a rare familial Parkinson’s disease is caused by c.1488+1G>A mutation in PTEN-induced kinase 1 (PINK1) gene." (PMID 33919699, 2021). "Mutations of three genes, PRKN, PINK1, and DJ-1 cause pure phenotypes usually characterized by levodopa-responsive Parkinson's disease." (PMID 33841314, 2021). "PINK1, a mitochondria-targeted serine/threonine kinase, enhances risk of Parkinson’s disease through a dominant-negative mechanism." (PMID 34354990, 2021). "This patient also carried homozygous mutations in the PINK1 gene, which are considered to be associated with early-onset Parkinsonism." (PMID 33964895, 2021). "Recessive mutations in the genes encoding parkin and PINK1 cause highly penetrant parkinsonism clinically similar to typical Parkinson’s disease." (PMID 34030727, 2021). "Similar abnormal mitochondrial morphology was detected in fibroblasts of Parkinson’s patient carrying PTEN-induced kinase 1 (PINK1) mutation and this morphology has detected to be associated with a decrease in DRP1 expression levels." (PMID 34518586, 2021). "HTRA2 is phosphorylated on activation of the p38 pathway, occurring in a PINK1‐dependent manner at a residue adjacent to a position found mutated in patients with Parkinson's disease." (PMID 34708890, 2021). "Ceramide accumulates in Parkinson’s disease–related PINK1 deficiency to initiate ceramide-mediated mitophagy as an alternative pathway to overcome defective PINK1-related mitophagy and the concomitant increased requirements for mitochondrial clearance." (PMID 34686591, 2021). "In fact, both of these proteins have been found mutated in this disease; PINK1 mutation causes Hereditary Early-Onset Parkinson meanwhile mutations in Parkin occurs in Autosomal recessive juvenile Parkinsonism (AR-JP)." (PMID 33782711, 2021). "Abnormal expression of the PTEN-induced serine/threonine–protein kinase 1 (PINK-1) or mutations in the PINK1 gene are linked to the recessively inherited form of Parkinson’s disease." (PMID 34838047, 2021). "Understanding the pathogenic mechanisms by which loss of function mutations in PINK1 and Parkin lead to neurodegeneration in Parkinson’s disease is central to defining better disease-modifying therapies." (PMID 32060339, 2020). "The next stage of the study explored the effects of a subtoxic concentration of VD and the role of iron upon wild-type and PINK-1 mutant loss-of-function flies as a model of familial Parkinson’s disease with a mitochondrial respiratory exchange deficit." (PMID 32937783, 2020). "PINK1 and Parkin are Parkinson's disease associated genes, and involved in nervous system development." (PMID 32318018, 2020). "Autosomal recessive mutations in the mitochondrial kinase PINK1 are associated with Parkinson disease." (PMID 32969543, 2020). "Both mutated in familial forms of Parkinson’s disease, PINK1 and Parkin are known relevant factors in MQC and inducers of the mitophagic pathway." (PMID 33304353, 2020). "Meanwhile, more than one hundred mutations have been reported on the PINK1 gene in families with Parkinson's disease so far." (PMID 32856414, 2020). "Autosomal recessive mutations in PTEN-induced kinase 1 (PINK1) represent the second most frequent cause of early onset Parkinson's disease (PD)." (PMID 32227113, 2020). "PINK1, mutated in Parkinson’s disease, interacts with the MICOS complex and regulates the size and number of crista junctions in neuronal mitochondria." (PMID 32581834, 2020).
Parkinson disease (continued). "Genome-wide association studies have identified various mutations that increase Parkinson’s disease susceptibility such as PINK1 and Parkin whose gene products regulate mitophagy." (PMID 33374212, 2020). "The link between Miro1 dysfunction and Parkinson's disease (PD) arose from studies that identified Miro1 as a target of the PD-associated proteins PINK1 and Parkin." (PMID 33041957, 2020). "PGAM5 deficiency disables PINK1-mediated mitophagy in vitro and causes a Parkinson’s-like phenotypes in mice model." (PMID 32671064, 2020). "In patients with idiopathic Parkinson’s disease, phosphorylation of HtrA2 at Ser142 is increased, and patients with Parkinson’s disease and mutations in the PINK1 gene have been shown to have diminished levels of Ser142-phosphorylated HtrA2." (PMID 33227899, 2020). "NCLX inhibition has been indicated in a familial form of Parkinson's disease, in which PINK-1 deficiency leads to a delayed Ca2+ efflux and mitochondrial Ca2+ overload in response to physiological Ca2+ stimulation." (PMID 33330511, 2020). "Parkinson’s disease and colon cancer share common genetic predispositions, such as PINK1, which is activated in opposite directions in neuronal and cancer tissues." (PMID 33308286, 2020). "A key pathway in the regulation of mitophagy involves the familial Parkinson’s disease-associated proteins PINK1 and Parkin and outer mitochondrial membrane protein Miro20." (PMID 32005875, 2020). "So, the PINK1 and Parkin together sense the distress of mitochondria and selectively target them for degradation, and the mutations of PINK1 or Parkin fail to clear damaged mitochondria, causing neuronal damage, leading to Parkinson's disease." (PMID 32454791, 2020). "Mutations in PINK1, which codes for a kinase involved in mitochondrial quality control, are associated with Parkinson’s disease; mutations in SLCO2A1, a prostaglandin transporter, cause chronic enteropathy." (PMID 33239447, 2020). "Research on Parkinson’s disease in C. elegans has also been made by studying the effects of mutation of the worm orthologues of PINK1 (pink-1), LRRK2 (lrk-1), PARKIN (pdr-1), and DJ-1 (dnaj-1.1 and dnaj-1.2)." (PMID 31947609, 2020). "The hereditary Parkinson’s disease-causing proteins PINK1 (PTEN-induced putative kinase 1) and Parkin play a role in regulating mitophagy, indicating the physiological importance of mitophagy in preventing neurodegenerative disorders." (PMID 32365950, 2020). "Consistently, the challenge of PINK1 or Parkin deficient mice with immunogenic stress leads to the onset of Parkinson disease-like symptoms." (PMID 32274386, 2020). "The upregulation of PINK1/Parkin axis, which is associated with early onset Parkinson’s disease, has been reported to exert neuroprotective effects." (PMID 33003463, 2020). "Some of these studies showed a strong association between PD and mutations in mitochondrial DNA, pointing out that mitochondrial respiratory disorder in familiar parkinsonism is associated with PINK1 mutation." (PMID 31284683, 2019). "The dopaminergic neurons that die in Parkinson’s disease are unusually prone to mutations in mitochondrial quality-control factors, such as Parkin and PINK1, to mitochondrial toxins like rotenone, and to dopamine oxidation products." (PMID 30654525, 2019). "Defects in mitophagy machinery are the main pathogenetic alterations in early-onset inherited parkinsonisms, in which the most relevant mutations occur in PINK1 and Parkin genes." (PMID 30791416, 2019). "An initial link between Miro1 and Parkinson's disease (PD) arose from the identification of Miro1 as a target of the PD-associated kinase PINK1 (PARK6) in a mitochondrial quality control pathway." (PMID 31303019, 2019). "Earlier biochemical and genetic studies revealed that PINK1, which has been associated to Parkinson's disease, works together with PRKN (also known as parkin) in the pathway involved in mitochondrial quality control." (PMID 31515286, 2019).
Parkinson disease (continued). "PINK1 mutations often drive neurological disorder like the Parkinson’s disease (PD) due to the impairment of normal mitochondrial functions." (PMID 31819034, 2019). "Together, these results indicate that MUL1 compensates for Parkinson’s phenotypes, caused by the loss of PINK1/Parkin or VSP35, by decreasing MFN2." (PMID 31156446, 2019). "Accordingly, two genes associated with Parkinson’s disease, mitochondrial kinase PTEN-induced kinase 1 (PINK1) and ubiquitin ligase Parkin, recognize damaged mitochondria and label them for autophagic degradation." (PMID 31882960, 2019). "Researchers have shown that in both humans and animals, the loss of function of PINK1 along with HTRA2 causes Parkinsonism." (PMID 30108499, 2018). "MFN2 is a key substrate of the PINK1/parkin couple, whose mutations are linked to the familial forms of Parkinson’s disease (PD)." (PMID 29491355, 2018). "On the other hand, mutations in the recessive genes including parkin (PRKN), PTEN-induced putative kinase 1 (PINK1) and DJ-1 are causative of early-onset parkinsonism shearing largely identical clinical phenotypes, but distinct neuropathology." (PMID 30618654, 2018). "Two proteins linked to Parkinson’s disease (PD), parkin, a cytosolic ubiquitin E3 ligase, and PINK1, a mitochondrially targeted kinase, have been shown to play key roles in mitophagy." (PMID 29500189, 2018). "The effect of PINK1 loss of function on Parkinson's disease models has been thoroughly documented and has highlighted the role of PINK1 in the maintenance of mitochondrial quality control and cellular homeostasis." (PMID 30116473, 2018). "Mutations in PINK1 (PARK6), a serine/threonine kinase involved in mitochondrial homeostasis, are associated with early onset Parkinson’s disease." (PMID 27975167, 2018). "Mitophagy is regulated in many metazoan cell types by Parkin and PTEN-induced putative kinase protein 1 (PINK1), while mutations in these genes are linked to Parkinson’s disease." (PMID 30545093, 2018). "PINK1 and Parkin are two genes which account for a large fraction of autosomal recessive early-onset forms of Parkinson’s disease and are now firmly associated to both mitochondria and redox homeostasis." (PMID 29529199, 2018). "Marf knockdown has been shown to completely suppress Pink1 and Parkin loss of function in Drosophila models of Parkinson’s disease in muscles and in the heart by preventing mitochondrial fusion." (PMID 29563863, 2018). "The Parkinson’s disease factors PINK1 and parkin are strongly implicated in stress-induced mitophagy in vitro, but little is known about their impact on basal mitophagy in vivo." (PMID 29500189, 2018). "Remarkably, PARKIN and PINK1 have been found mutated in Parkinson Disease (PD) patients, suggesting the importance of this pathway in dysfunctional mitochondria clearance by autophagy." (PMID 30687233, 2018). "Mutations in the human kinase PINK1 (hPINK1) are associated with autosomal recessive early-onset Parkinson's disease (PD)." (PMID 28980524, 2017). "In the cerebellum, the most salient result was a significant effect for the KEGG pathway “Parkinson’s disease”, but this biomathematical finding was mainly due to the loss of Pink1 transcript." (PMID 28768533, 2017). "Parkinson disease 6 (PARK6, #605909) results from mutations in PINK1 coding a mitochondrial protein (PTEN-induced putative kinase 1), causing increased susceptibility to cellular stress and apoptosis." (PMID 29170650, 2017). "Mutations that affect PINK1 are often seen in people with early-onset Parkinson’s disease and cases that are inherited through families." (PMID 28980524, 2017). "CI dysfunction was also reversed by expression of the phospho-mimetic Ndufa10 in cells from Parkinson’s patients carrying Pink1 mutations." (PMID 29267372, 2017). "Autosomal recessive inherited loss-of-function mutations in human PTEN-induced kinase 1 (hPINK1), represent the second most frequent cause of early-onset Parkinson’s disease (PD)." (PMID 28980524, 2017).